EIF4E1B (eukaryotic translation initiation factor 4E family member 1B)
Description:
Recognizes and binds the 7-methylguanosine-containing mRNA cap during an early step in the initiation of protein synthesis and facilitates ribosome binding by inducing the unwinding of the mRNAs secondary structure.
Synonyms: FLJ36951
Tractability: No criterion of Open Targets' tractability assessment is met for any kind of drug.
Gene: Protein-coding gene on chromosome 5 (176,630,582 to 176,646,644, forward strand). Ensembl gene ENSG00000175766.
Gene Ontology:
Molecular function: protein binding; RNA 7-methylguanosine cap binding; translation initiation factor activity; RNA binding
Biological process: translational initiation
Cellular component: eukaryotic translation initiation factor 4F complex; cytoplasm
Genetic constraint (gnomAD): Loss-of-function variants: 22 observed, 28.97 expected, observed/expected ratio (o/e) 0.76, 90% interval 0.54 to 1.09. The upper end of that interval is the gene's LOEUF score, 1.09, which puts it in group 4 of 6, group 1 being the genes least tolerant of losing a copy. Missense variants: 290 observed, 281.05 expected, observed/expected ratio (o/e) 1.03, 90% interval 0.94 to 1.14. Synonymous variants: 126 observed, 113.03 expected, observed/expected ratio (o/e) 1.11, 90% interval 0.96 to 1.29.
Homologues: Orthologues: chimpanzee EIF4E1B (98% identical), dog EIF4E1B (81% identical), pig EIF4E1B (81% identical), guinea pig EIF4E1B (80% identical), rat AC135142.1 (74% identical), rabbit EIF4E1B (71% identical), mouse Eif4e1b (67% identical), zebrafish eif4e1b (55% identical), Drosophila melanogaster eIF4E4 (37% identical), Drosophila melanogaster eIF4E1 (36% identical), Drosophila melanogaster eIF4E7 (36% identical), Drosophila melanogaster eIF4E5 (34% identical), and 6 more. Paralogues in human: EIF4E (57% identical), EIF4E2 (29% identical), EIF4E3 (22% identical).
Diseases named in the same sentence as EIF4E1B in open-access papers:
EIF4E1B is named in the same sentence as 9 diseases in open-access papers, as found by Europe PMC text mining. Sharing a sentence is not in itself a finding about the gene and the disease. The quoted sentences say what the papers report.
glioma (5 papers, 2021 to 2024). A benign or malignant brain and spinal cord tumor that arises from glial cells (astrocytes, oligodendrocytes, ependymal cells). "APOBEC3F (HR: 0.395, 95%CI: 0.201–0.778, p = 0.007) and EIF4E1B (HR: 0.568 95%CI: 0.342–0.943, p = 0.029) were positively associated with clinical outcomes in glioma patients." (PMID 33634155, 2021). "EIF4E1B was found to associate with OS-SEs most significantly among differentially expressed m7G regulators and we also reported the dual functions of this gene depending on glioma grade." (PMID 36036011, 2022). "The data showed that ADARB2 and EIF4E1B had lower expression levels in glioma grade IV than II samples (both p < 0.001)." (PMID 33634155, 2021). "While exploring the correlation between signature genes and the ASEs in glioma, we found that EIF4E1B was a key regulator and might play dual roles depending on glioma grade." (PMID 36036011, 2022). "Moreover, the variance in expression levels of DCPS, EIF4E1B, NUDT1, and NUDT16L1 between glioblastomas (GBMs) and low-grade gliomas (LGGs) suggests their involvement in the progression of glioma malignancy." (PMID 39061374, 2024). "However, the expression and function of EIF4E1B gene and eIF4E1b protein have not been reported in humans, our results showed that the mRNA level of EIF4E1B decreased in glioma tissue, indicating possible anti-tumor effects." (PMID 36036011, 2022).
Infertility (1 paper, 2024). "Mutations in eIF4ENIF1 cause infertility in women, in agreement with both eIF4E1b and eIF4ENIF1 working together to regulate maternal mRNA dormancy." (PMID 38177902, 2024).
ovarian carcinoma (1 paper, 2024). A malignant neoplasm originating from the surface ovarian epithelium. "Consistent with this phenotype, genes involved in cell adhesion, such as cdh2 and cd44a, which have been implicated in ovarian cancer, were upregulated at the mRNA level in eif4e1b mutant gonads (F and Dataset EV7)." (PMID 38177902, 2024).
tumor (8 papers, 2022 to 2024). "In our study, we found high expression of EIF4E1B, LARP1, GEMIN5, and DCP2 in tumor tissues, which seems to be consistent with our results." (PMID 36003341, 2022). "Since eIF4E has been implicated in cancer, the upregulation of eIF4E1c may contribute to the rare development of tumor-like gonads without oocytes in eif4e1b mutant fish." (PMID 38177902, 2024). "The protein expressions of METTL1, NSUN2, EIF4G3, LARP1, NCBP1, and NCBP2 were higher in tumor tissues than in normal tissues; however, the protein expressions of WDR4, EIF4E1B, and NCBP2L were negative in both tumor and normal tissues." (PMID 35785179, 2022).
cancer (2 papers, 2022 to 2024). A tumor composed of atypical neoplastic, often pleomorphic cells that invade other tissues. "We found 5 primary regulator genes (EIF4E1B, METTL1, NUDT11, NUDT10 and NUDT4B) were differential expressed in more than 15 cancer types." (PMID 36092891, 2022).
infection (1 paper, 2017). The state of being infected such as from the introduction of a foreign agent such as serum, vaccine, antigenic substance or organism. "Infection foci on the inoculated leaves of eif4e, eif4e1b, eif4e1c, and eifiso4e mutants were nearly the same size as those on the A. thaliana ecotype Columbia-0 (Col-0) leaves." (PMID 28059075, 2017).
EIF4E1B also shares sentences with these, for which no sentence is quoted: glioblastoma (1 paper); pancreatic adenocarcinoma (1); thymoma (1).